EML4 (EMAP like 4)
Diseases named in the same sentence as EML4 in open-access papers (continued):
Sharing a sentence is not in itself a finding about the gene and the disease.
tumor (continued). "Using two genetically engineered mouse models (GEMMs), we find that EML4–ALK variant 1 can drive lung tumorigenesis and these murine tumors, as well as primary tumor-derived organoids, clearly show the condensates of EML4–ALK protein, further supporting the findings from in vitro study." (PMID 33976114, 2021). "Consistently, we found strong EML4–ALK expression in tumor areas." (PMID 33976114, 2021). "Both the EML4-ALK gene fusion and the promoter TERT variant were confirmed in the primary tumor." (PMID 33878728, 2021). "Indeed, the combination of ALK and MEK inhibition was highly effective at suppressing tumor growth in a preclinical model of EML4‐ALK NSCLC." (PMID 34058070, 2021). "Molecular analysis of tumor tissue showed an EML4-ALK gene fusion." (PMID 33878728, 2021). "The wild-type EML4–ALK was able to drive fast tumor growth even after 11 days of transplantation." (PMID 33976114, 2021). "Similarly, RNA obtained from tumor tissue with 60% tumor content was known to have 2028 fusion copies of EML4-ALK." (PMID 33556149, 2021). "We next tested whether EML4cc peptides can limit growth of tumor cells with EML4-ALK rearrangements." (PMID 32300555, 2020). "Further molecular analysis of the tumor tissue revealed an EML4:NTRK3 fusion." (PMID 33353026, 2020). "Moreover, LC-associated EML4/ALK1 translocation originated from F-circRNAs, which are functionally relevant (tumor promoting), and represented a novel entry point for LC diagnosis." (PMID 32071550, 2020). "These types of modifications might enhance the anti-tumor effects of our EML4cc peptide against EML4-ALK fusion positive cancers, and are being considered for future studies." (PMID 32300555, 2020). "Given that Notch has been found to have a critical role in EMT and tumor hypoxia signaling crosstalk, it stands to reason to infer that the inhibition of Notch may sensitize EML4-ALK TKI resistant NSCLCs." (PMID 32784481, 2020). "Then, we used the non-tumor NAT specimens to investigate whether transcription of EML4 is constitutively activated even in normal lung cells." (PMID 30943926, 2019). "Depending on the tumor type, the RAS/MEK/ERK pathway acts alone or cooperates with other oncogenic pathways [e.g., JNK-, PI3K/AKT-, IL-6/STAT3, and echinoderm microtubule associated protein-like 4/anaplastic lymphoma kinase (EML4/ALK)-dependent pathways] in increasing PD-1L." (PMID 31117237, 2019). "In addition to EGFR, ALK-rearrangement testing is also routine and there are a number of targeted therapies for tumours harbouring the EML4-ALK fusion gene." (PMID 30470932, 2019). "Additional evidence of the specificity of ponatinib’s antitumor activity was observed when ponatinib had minimal effects on an in vivo isogenic Ba/F3 tumor model dependent on oncogenic EML4-ALK in comparison with the approved ALK inhibitor crizotinib (200 mg/kg)." (PMID 30038711, 2018). "Furthermore, we demonstrate regulation of MYC promoter activity by ALK in ALK+ cell lines and non-tumor NIH3T3 ectopically expressing EML4-ALK." (PMID 29507657, 2018). "A tumor containing the EML4-ALK fusion had the highest ALK expression." (PMID 30361512, 2018). "Further, the reduction of tumor outgrowth upon deletion of the HELP domain may point to an additive role of the EML4 fusion partner in driving oncogenesis." (PMID 29189709, 2017). "RNAseq and RT-PCR further revealed that the tumor harbored an EML4-ALK fusion gene." (PMID 28535796, 2017). "Additionally, the multiplex RT-PCR can sensitively detect not only certain ALK fusion gene variant even in formalin-fixed paraffin-embedded (FFPE) tissue sections, but also the abundance of EML4-ALK positive cells in NSCLC tumor tissues." (PMID 29088875, 2017). "Analysis for EGFR mutations and EML4-ALK translocation was not possible due to insufficient tumor material for molecular testing." (PMID 26959886, 2016). "In addition, OTX015 presented good oral bioavailability and induced tumor regression in EML4-ALK(+) xenografts." (PMID 27835869, 2016).
tumor (continued). "EML4-ALK v1 was detected in her tumor and platelets at baseline in March 2012." (PMID 26544515, 2016). "The tumor was negative for epidermal growth factor receptor mutation but positive for the EML4-ALK fusion oncogene according to fluorescence in situ hybridization." (PMID 26964537, 2016). "Importantly, combinational treatment with rapamycin and crizotinib leads to synergistic anti-tumor effects on EML4-ALK+ NSCLC cells as well as on those resistant to crizotinib." (PMID 26517679, 2015). "Notably, treatment with rapamycin, a CSC targeting agent, attenuates stem-like phenotypes of the EML4-ALK+ cells, which increased capability of tumor formation and higher expression of stemness-associated molecules such as ALDH, NANOG, and OCT4." (PMID 26517679, 2015). "Moreover, the combinational treatment with rapamycin and crizotinib leads to synergistic anti-tumor effects on EML4-ALK+ NSCLC cells as well as on those that acquired resistance to crizotinib." (PMID 26517679, 2015). "We apply TRUP to RNA-seq data of different tumor types, and find it to be more sensitive than alternative tools in detecting chimeric transcripts, such as secondary rearrangements in EML4-ALK-positive lung tumors, or recurrent inactivating rearrangements affecting RASSF8." (PMID 25650807, 2015). "Since FISH has been approved as a reliable diagnostic test for crizotinib (ALK inhibitor) treatment, our findings might suggest that high abundance of EML4-ALK positive cells in tumor tissues could also be related to the treatment response to ALK inhibitors." (PMID 23951022, 2013). "Among the three detection methods, RT-PCR could detect not only the presence of EML4-ALK fusion gene and their variant types, but also the abundance of EML4-ALK positive cells in NSCLC tumor tissues." (PMID 23951022, 2013). "On the other hand, the EML4-ALK-positive tumor of the right lung was an invasive cancer." (PMID 23617234, 2013). "We collected mRNA from the same tumor specimens using Pinpoint Slide RNA Isolation System in order to clarify whether there was EML4–ALK (echinoderm microtubule-associated protein-like 4 gene and the anaplastic lymphoma kinase gene) fusion gene in each tumor." (PMID 23714228, 2013). "The tumor was negative for epidermal growth factor receptor mutation but positive for the echinoderm microtubule-associated protein-like 4-anaplastic lymphoma kinase (EML4-ALK) fusion oncogene according to fluorescence in situ hybridization." (PMID 26964537, 2016). "We analyzed tumor regions of 82 formalin‐fixed paraffin‐embedded (FFPE) tissue sections with 6, 23, 31, and 22 samples from the EML4–ALK, EGFR, KRAS, and WT sample groups, respectively." (PMID 40621945, 2025). "Research indicates that EML4-ALK fusion proteins and EGFR activation can upregulate PD-L1 expression, promoting tumor immune evasion." (PMID 41487577, 2025). "TKI-targeted inhibition of ALK can disrupt the EML4-ALK compartment, potentially interfering with the transcriptional regulation between MAPK and SWI/SNF, thereby affecting tumor cell proliferation." (PMID 40416876, 2025). "Ceritinib treatment slowed tumor growth and improved survival in mice injected with RDAA and ALK-rearranged (EML4-ALK) H1299 cells compared with control mice." (PMID 40246819, 2025). "The EML4-ALK fusion gene leads to the aberrant activation of ALK kinase, thereby facilitating the growth and proliferation of tumor cells." (PMID 40584293, 2025). "Alectinib demonstrated potent antitumor activity in both in vitro and in vivo models against tumor cell lines harboring ALK gene alterations, including NSCLC cells with the EML4-ALK fusion." (PMID 40870997, 2025). "F-ciricEA-4a, harboring “AAAA” motif at junction site, was investigated for its role in cancer, where it showed oncogenic activity independently from the onco-genic fusion transcript and protein EML4-ALK, hence contributing to tumor development." (PMID 38919532, 2024).
tumor (continued). "Subsequent investigations demonstrated that inhibiting YAP1 genetically or pharmacologically suppressed tumor growth in ALK-TKI-resistant lung adenocarcinoma cells, EML4-ALK transgenic mice, and tumor xenograft models." (PMID 38499647, 2024). "For example, cancer RNA biomarkers such as KRAS, PCA3, PIK3CA mutants, EGFRvIII, FOLH1, KLK2, KLK3, EML4-ALK, and NYP have been reported to be sequestered by platelets that actively uptake tumor-derived material." (PMID 39274207, 2024). "Although clinical trial data regarding the use of this drug are currently limited, in EML4–ALK xenograft models in mice, Brigitanib exhibits a dose-dependent inhibition of tumor growth, tumor burden, and prolonged survival." (PMID 37375228, 2023). "Vaccination of mice significantly increased the number of tumour‐infiltrating T lymphocytes specific for ALK, compared with mice injected with EML4‐ALK tumour cells." (PMID 37795653, 2023). "The tumor-targeting potentialof [methylpiperazine-11C]brigatinib wasevaluated in four NSCLC cell lines; A549, HCC827, EML4–ALKfusion-A549, and H2228." (PMID 37647220, 2023). "In all three EML4-ALK cell line models, significant tumor shrinkage was elicited by alectinib, but was followed by prompt tumor progression within three to four weeks of initiating treatment, despite continuous TKI therapy." (PMID 36739466, 2023). "The targeted next generation sequencing (NGS)-based genomic profiling of his tumor using formalin-fixed and paraffin embedded (FFPE) tissue was performed and a EML4-ALK fusion was detected." (PMID 37950305, 2023). "The optimal compound 9j exhibited excellent activity for both EGFR T790M/L858R, EML4-ALK kinases, and inhibition activity against tumor cell proliferation." (PMID 36903251, 2023). "EML4-ALK exhibits potent oncogenic properties both in vitro and in vivo, in which tumor development can be rapidly suppressed using ALK TKIs." (PMID 35620280, 2022). "The combination of an ALK TKI with HSP90 inhibition not only yielded synergism in Ba/F3 cells expressing EML4-ALK V1, but also induced apoptosis in vitro and tumour regression in vivo of patient-derived cells expressing V1." (PMID 35884511, 2022). "In the advanced tumor stages, patients with ACA had ALK fusions with 2.2% frequency (14/650), and the fusion partner was always EML4." (PMID 36293366, 2022). "Here, we employ lineage-tracing mouse models to investigate the cell of origin of Eml4-Alk LUAD, and show that Club and Alveolar type 2 (AT2) cells give rise to tumours." (PMID 35931677, 2022). "Another case identified an EML4::ALK rearrangement in LCNEC with crizotinib resistance, suggesting that perhaps ALK-positive LCNEC is derived from ALK-positive ACA via tumor plasticity." (PMID 35200571, 2022). "Molecular testing showed EGFR amplification and -EML4-ALK fusion, the TMB was 1.6 muts/Mb and the tumor was PD-L1 positivewith a TPS of 3% on immunohistochemistry." (PMID 36523965, 2022). "XMU‐MP‐5 blocks ALK signaling pathways and inhibits the proliferation of cells harboring either wild‐type or mutant EML4‐ALK in vitro and suppresses tumor growth in xenograft mouse models in vivo." (PMID 34845836, 2022). "Molecular testing showed an EML4-ALK (E18:A20) fusion, and PD-L1 positivity, with a tumor proportion score (TPS) of 10% on IHC." (PMID 36523965, 2022). "Guarnerio and colleagues reported that oncogenic chromosomal translocations lead to the generation of fusion-circRNAs (F-circRNAs): one such F-circRNA, termed f-circEA1, is generated by the EML4-ALK fusion gene and was shown to promote tumor development." (PMID 34680298, 2021). "NGS results revealed that both EML4‐ALK fusion and MINPP1 and PAPSS2‐PTEN fusion were present in the patient's tumor tissue and ctDNA in blood." (PMID 33225619, 2021).
tumor (continued). "To determine whether aneuploidy caused by Mad2 overexpression accelerates tumor formation driven by Eml4-Alk oncogene, we assessed tumor burden in mice 16 weeks after adenoviral infection in control (Alk) and aneuploid groups (Alk+Mad2) measured by lung weight as well as by tumor area." (PMID 34885137, 2021). "ALK rearrangement results in abnormal EML4-ALK fusion tumor gene, which activates ALK tyrosine kinase, leading to inhibition of apoptosis and promotion of tumor cell proliferation." (PMID 34630126, 2021). "Obvious condensate formation of EML4–ALK proteins was observed in both murine lung tumors and tumor-derived organoids." (PMID 33976114, 2021). "In EML4-ALK cancer cell lines, administration of synthetic EML4cc peptide elicited a decrease of phosphorylation of ALK leading to reduction in tumor cell growth." (PMID 32300555, 2020). "Using a fluorescent protein system to quantify protein-protein interactions of EML4-ALK and EML4cc, we demonstrated that co-expression of EML4cc suppressed EML4-ALK assembly concomitant with decreasing the rate of tumor growth in vitro and in vivo." (PMID 32300555, 2020). "Consistently, ALK inhibition with crizotinib reversed the stem-like phenotypes of EML4-ALK+ tumor cells, suggesting ALK signaling is a central molecular axis in the stem-like phenotype of EML4-ALK+ tumor cells." (PMID 26517679, 2015). "We report here that an EML4-ALK-derived peptide-specific human CTL clone recognized peptide-pulsed T2 cells and HLA-A*02:01-positive and EML4-ALK-positive tumor cells pretreated with IFN-γ." (PMID 24842630, 2014). "Since we only evaluated 100 tumor cells in FISH test for each tumor, it was reasonable that high abundance of EML4-ALK positive cells in tumor tissues would have higher chance to be positive for FISH." (PMID 23951022, 2013). "PF-02341066 (crizotinib) is a novel dual c-Met and EML4-ALK inhibitor, and preclinical studies have shown that treatment with ALK inhibitors leads to drastic tumor regression in xenograft models." (PMID 23254764, 2013). "20/25 IBC patient tumor samples had some type of ALK genetic aberrations including ALK copy numbers, ALK gene amplification and in the case of 1 IBC patient, EML4-ALK translocation." (PMID 24102046, 2013). "We confirmed that phosphorylation of both EML4–ALK and ERK was inhibited in tumour xenografts treated with the combination of TAE684 and AZD6244, but not in those treated with TAE684 alone, consistent with the results of our in vitro experiments." (PMID 22240786, 2012). "Given the similarities in tumor-driving mechanisms between RDAA and EML4-ALK rearrangement/fusion reveal by this study, we hypothesize that RDAA-positive tumors may also exhibit a strong metastatic potential." (PMID 40246819, 2025). "Further research has shown that EML4-ALK initially promotes the formation of LUAD and drives squamous transformation in the late stage, altering the morphology and characteristics of the tumor." (PMID 40568576, 2025). "However, 19 months after initiating osimertinib, an EML4-ALK fusion emerged, indicating a change in the tumor’s genetic landscape." (PMID 39135785, 2024). "Among the most frequent 5′-partners are EML4 (echinoderm microtubule-associated protein-like 4) in NSCLC and STRN (striatin), NPM1 (nucleophosmin), and TPM3 (tropomyscin 3) in non-NSCLC neoplasms." (PMID 39594806, 2024). "A F-circEA, a circRNA generated by EML4-ALK fusion gene, is another potential liquid biopsy biomarker as it specifically exists in the plasma of EML4-ALK-positive NSCLC patients and contributes to tumor development by promoting cell migration and invasion." (PMID 38501058, 2024). "However, there was a striking immune response when EML4‐ALK tumours were grown in the flank of the mouse, and tumours in this context were rejected after treatment with ICIs." (PMID 37795653, 2023).
tumor (continued). "Taken together, we could show that CIK cells in combination with crizotinib and nivolumab can enhance the anti-tumor immune response through FasL activation, leading to increased IFN-γ and granzyme B, but only in NCI-H2228 cells with EML4-ALK rearrangement." (PMID 35646685, 2022). "Eml4-Alk tumors stained positively for α-smooth muscle actin (αSMA), a canonical vascular smooth muscle cell marker that can be expressed by tumor pericytes but is often absent in quiescent pericytes in normal tissues." (PMID 36192379, 2022). "Remarkably, regardless of the originating cell type, all Eml4-Alk tumours were positive for the AT2 cell marker, SPC." (PMID 35931677, 2022). "Indeed, analyses of circulating tumor cells revealed high levels of chromosomal instability in ALK-positive NSCLC patients that were resistant to ALK inhibitor treatment, and it will be interesting to determine whether this correlates with the EML4-ALK variant expressed." (PMID 35656694, 2022). "We identified Club and AT2 cells as the main cell types implicated in Eml4-Alk LUAD development and showed that Eml4-Alk fusion gene in AT1, Ciliated or Basal cells did not give rise to tumours." (PMID 35931677, 2022). "By integrating scRNA-seq with whole-genome bisulfite sequencing analysis of Eml4-Alk tumours, we show that LUADs, unlike other tumour types, are only partly dependent on their originating cell type." (PMID 35931677, 2022). "Thirdly, we did not carry out subgroup analyses according to tumor stage, oncogenic alteration (e.g., EGFR mutation, EML4-ALK fusion, KRAS mutation), expression status of PD-1/PD-L1, etc. due to the limitations of the data." (PMID 34497760, 2021). "The mean tumor size of EML4-ALK positive cases was significantly larger than in EML4-ALK negative cases (mean±SD, 5.54±3.34 vs 3.61±2.02, 0.037)." (PMID 32876329, 2021). "Importantly, the EML4–ALK condensates were clearly detectable in these murine lung tumors and tumor-derived organoids." (PMID 33976114, 2021). "Curiously, however, F-circEA-2a was present in the tumor but not in the plasma of NSCLC patients (n = 3) with the EML4-ALK fusion gene." (PMID 34680298, 2021). "EML4‐ALK and MINPP1 & PAPSS2‐PTEN fusions were found to be present in tumor tissue and blood." (PMID 33225619, 2021). "None of these cells were able to form a growing tumor, while EML4-ALK-expressing mouse NIH/3 T3 cells as a positive control consistently formed progressively growing tumors." (PMID 33761896, 2021). "Since the tumor size at this time point was small, we also compared the results to animals that expressed Mad2 but were not infected with the Eml4-Alk virus." (PMID 34885137, 2021). "As expected, treatment with 30 mg/kg gilteritinib-induced tumor shrinkage in mice carrying WT EML4-ALK harboring JFCR-028-3 or H3122 tumors without body weight loss." (PMID 33627640, 2021). "Treatment with crizotinib at a low concentration suppressed the growth of the EML4-ALK–transformed (AC) tumor cells, but not those of the KRAS(G12V)-expressing (KC) tumor cells." (PMID 33348616, 2020). "ALK-EML4 rearrangement is the consequence of a gene fusion in chromosome 2 between ALK gene and EML4 gene which leads to the activation of the tyrosine kinase domain of ALK protein that enhances tumor growth and proliferation." (PMID 32460789, 2020). "A probe recognizing EML4 gene was used as reference, given this gene is located in chromosome 17, which was almost never affected in the primary tumours." (PMID 32030896, 2020). "In the other ALK fusion–negative NAT specimens, more EML4 mRNA was expressed at each exon than in the tumor tissues." (PMID 30943926, 2019). "Meanwhile, the N-terminal EML4 protein was expressed in all tumor tissues independent of ALK fusion status." (PMID 30943926, 2019).